INS (insulin)
Diseases named in the same sentence as INS in open-access papers (continued):
Sharing a sentence is not in itself a finding about the gene and the disease.
Insulin resistance (continued). "The glucose‐lowering effects of thiazolidinediones are due to increased disposal of glucose into adipose tissues along with increased expression of insulin sensitizing factors, such as adiponectin, and decreased expression of proteins that promote insulin resistance such as FGF‐21." (PMID 31782258, 2019). "They explained that Nrg4 could stimulate insulin release from islet cells and improve insulin resistance under metabolic stress in mice." (PMID 31815951, 2019). "Mice fed a long‐term HFD showed significantly increased obesity and insulin resistance‐related phenotypes, including elevated body weight, fat mass, and blood glucose, and exhibited impaired tolerance to both glucose and insulin, relative to age‐matched NC‐fed mice (Fig EV2B and C)." (PMID 31464373, 2019). "In addition, insulin resistance suppresses adipose tissue lipolysis and increases de novo lipogenesis through a suppression of insulin ability, although the insulin secretion is increasing." (PMID 31687367, 2019). "Contextually, insulin secretion is implemented to balance peripheral insulin resistance." (PMID 31323991, 2019). "Hsa-miR-181a-2-3p levels, on the other hand, correlated negatively with genes leading to the transport of GLUT4 to the plasma membrane in the insulin signaling pathway, while it seemed to activate the route leading to insulin resistance in the type II diabetes mellitus pathway." (PMID 31222113, 2019). "Adipose tissue and blood samples were obtained for the analysis of cytokines, Th17 and Treg markers, and insulin sensitivity blood parameters, for comparisons with those of the normal control group, IL-6-blocked control group, and insulin resistance control group." (PMID 31218568, 2019). "Insulin stimulates protein and muscle synthesis; thus, impairments in insulin signaling could lead to insulin resistance, affecting muscle synthesis." (PMID 30823497, 2019). "Fe accumulation in the liver may lead to insulin resistance by interfering with the insulin capacity to inhibit hepatic glucose production." (PMID 30430418, 2019). "Therefore, we examined plasma insulin levels in both fasting and postprandial conditions and also computed homeostasis model assessment-estimated insulin resistance (HOMA-IR)." (PMID 30792482, 2019). "Insulin resistance may lead to compensatory hyperinsulinemia when pancreatic beta cells increase insulin secretion to maintain normal blood glucose." (PMID 30605491, 2019). "Alternatively, an increased proportion of small adipocytes may represent a compensatory mechanism that develops only after insulin resistance is established as an attempt to maintain glucose–insulin homeostasis." (PMID 31336724, 2019). "The mitochondrial biogenesis master regulator; peroxisome proliferator-activated receptor γ coactivator 1α (PGC-1α) is required to maintain insulin-mediated signaling as well as mitochondrial function and integrity, thus underscoring its importance in the development of insulin resistance." (PMID 31737638, 2019). "Furthermore, high oxidative stress has been related to elevated insulin resistance, poor insulin sensitivity, atherosclerosis and hypertension." (PMID 31745461, 2019). "Consequently, this reduces insulin sensitivity and disrupts cellular glucose uptake, leading to insulin resistance." (PMID 31878222, 2019). "Thus, ablation of the IRS-1/2 receptors by overexpression of inflammatory molecules suppresses the insulin signaling pathway and results in insulin resistance." (PMID 31551782, 2019). "Insulin resistance describes a reduced effect of insulin on its target tissues." (PMID 31474943, 2019). "In general, more severely ill patients might have higher insulin needs (due to more insulin resistance) and higher glucose needs (due to conditions like liver failure, ileus, etc.)." (PMID 30742240, 2019).
Insulin resistance (continued). "Many categories of hypoglycemic agents are presently used in the management of type 2 diabetes, which acts through a diverse mechanism of actions, such as in promoting insulin secretion, minimizing insulin resistance, or improving insulin penetration into the cells." (PMID 31340601, 2019). "In this context, endothelial dysfunction is a disorder that is constantly associated with both type I (insulin-dependent) and type II diabetes, characterized by high concentrations of serum insulin and by insulin resistance, occurring at the early stages of the disease." (PMID 31226852, 2019). "Insulin resistance was improved via the consumption of dietary chokeberry and dried jujube fruits according to various indicators (serum insulin level, fasting blood glucose level, homeostatic model assessment-insulin resistance score, and oral glucose tolerance test value)." (PMID 31171927, 2019). "Moreover, overexpression of FATE1, an organelle uncoupler, reduces mitochondria-SR interactions and dampens insulin signalling both in vivo and in vitro, whereas inducing organelle coupling protects human myotubes from palmitic acid-induced insulin resistance." (PMID 31130874, 2019). "Glutamate excitotoxicity is implicated in the pathogenesis of numerous diseases, such as stroke, traumatic brain injury, and Alzheimer’s disease, for which insulin resistance is a concomitant condition, and intranasal insulin treatment is believed to be a promising therapy." (PMID 31611766, 2019). "The HOMA-IR is the best surrogate marker of insulin resistance, but the cost for the determination of circulating insulin might be a barrier." (PMID 31465427, 2019). "Based on our data on insulin resistance, we can speculate that insulin sensitivity is better preserved among subjects adhering to the Mediterranean diet who eat SSC foods." (PMID 31771147, 2019). "In rodent models of T2DM, brain insulin resistance impairs hippocampal-based cognitive function and neuroplasticity mainly by a combination of reduced insulin transport across the blood-brain barrier (BBB), mitochondrial dysfunction, ROS overproduction, and neuroinflammation." (PMID 31248127, 2019). "According to these theories, myoinositol could reduce the insulin resistance in pregnancy and myoinositol supplementation could increase the action of endogenous insulin." (PMID 31886278, 2019). "It was therefore tested whether methylamine could mitigate insulin resistance via a direct facilitation of insulin secretion." (PMID 31409018, 2019). "As a result, T2DM’s state of insufficient insulin production or insulin-resistance can have detrimental complications, including macrovascular diseases such as hypertension, coronary artery disease, heart attacks and strokes; or microvascular diseases such as neuropathy, nephropathy, and cancer." (PMID 31888124, 2019). "Impairments of any part of the insulin signaling pathway can lead to insulin resistance." (PMID 31461405, 2019). "While we did not examine the specific mechanisms behind these observations, current preclinical literature in this area may provide insight into why obesity and insulin resistance attenuate orphan nuclear receptor responses to insulin." (PMID 30912283, 2019). "Others hypothesise that increased adipose tissue increases circulating levels of adiponectin and leptin, inflammatory proteins, oxidative stress, insulin and insulin resistance and abnormalities in lipid metabolism." (PMID 31266462, 2019). "Saturated fatty acids, in particular, inhibit insulin signal transduction by activating a variety of kinases and subsequently result in decreased glucose uptake and glycogen synthesis, as well as peripheral insulin resistance." (PMID 31137828, 2019). "First, our study cohort was small because we recruited patients with both T2DM and osteoporosis who were not having insulin therapy so that we could employ HOMA-IR and HOMA-β as surrogate markers of insulin resistance and insulin secretion." (PMID 31764838, 2019).
Insulin resistance (continued). "After 6 hours of fasting insulin resistance assessed according to the homeostatic model (HOMA-IR) was decreased in mice with access to RW compared to mice on the same diet without RW access indicating that voluntary activity increases insulin sensitivity." (PMID 30860981, 2019). "Previous studies have shown that EFT is closely related to insulin levels in serum in addition to Resistin mRNA levels and may be involved in the formation of insulin resistance." (PMID 30630489, 2019). "Only one study evaluated the outcomes of glucose, insulin, and insulin resistance (HOMA-IR)." (PMID 32153942, 2019). "In order to better study insulin resistance in this setting and to explore its relation to macrophage number, more direct and sophisticated methods of insulin sensitivity quantification may need to be performed." (PMID 30719456, 2019). "In this review, we examine the relevance of insulin signaling in brain, especially for dopaminergic function, the relationship between insulin resistance and PD and finally we give an overview of the rationale underlying the use of drugs currently used for T2D in PD patients." (PMID 31474827, 2019). "However, the normal insulin levels during pregnancy do not adequately occur in all pregnancies, except in those with preexisting insulin resistance or women who cannot increase insulin secretion, resulting in GDM." (PMID 31772944, 2019). "Recognizing the link between insulin sensitivity and the mechanisms regulating energy balance, it could be speculated that by combating insulin resistance SSE also affects energy balance." (PMID 31847157, 2019). "Whether exogenous insulin in type 2 diabetic treatment has a similar physiological effect as endogenous hyperinsulinemia in insulin resistance warrants further investigation." (PMID 31200528, 2019). "Moreover, placental insulin resistance, associated with a reduction in phosphorylated AKT (p-AKT), found in diet treated GDM, can be reversed by insulin treatment during pregnancy." (PMID 30873116, 2019). "Elevated plasma AC levels could result in the alternation of insulin signaling and lead to insulin resistance." (PMID 31450550, 2019). "The main reason for insulin resistance was that the binding of insulin antibodies and insulin inhibits the transport of insulin targets, the insulin receptors on the target cells were reduced in hyperinsulinaemia, and the acidosis made the body to become less sensitive to insulin." (PMID 31072232, 2019). "Published data support the hypothesis that anthocyanins lower blood glucose as a result of overcoming insulin resistance, protection of β cells, stimulated secretion of insulin, and slowing down digestion of sugars in the small intestine." (PMID 31817505, 2019). "As a result, the fetus may adapt to malnutrition by reducing capacity to produce insulin and by occurrence of insulin resistance." (PMID 30944826, 2019). "Recent studies have found high concentrations of apelin in obese individuals and in type 2 diabetes patients, while showing correlations of apelin with homeostatic model assessment-insulin resistance, body mass index, total cholesterol, low-density lipoprotein cholesterol, and insulin." (PMID 30696454, 2019). "Insulin resistance is a status in which cells do not respond properly to the insulin and causes high blood glucose concentration, leading to type 2 diabetes." (PMID 31289664, 2019). "RBP4 is thought be related to obesity, insulin resistance, type-2 diabetes, and metabolic syndrome and is suggested to be an early indicator of the development of insulin resistance and metabolic syndrome, and that this adiponectin is more sensitive to insulin than leptin, IL-6, and CRP." (PMID 30761880, 2019).
Insulin resistance (continued). "Moreover, another report demonstrated that capsules containing Iranian propolis (1.5 g/day for 8 weeks, n = 30) led to decreased FBG, blood insulin, HbA1C, and insulin resistance compared with the placebo treated group (n = 30)." (PMID 31805752, 2019). "Finally, HOMA-IR is used to quantify insulin resistance, and insulin is a critical regulator of virtually all aspects of adipocyte biology." (PMID 31138858, 2019). "Type 2 diabetes mellitus (T2DM), a metabolic disorder known by high blood glucose, is caused by the combination of not-sufficient secretion of insulin and insulin resistance." (PMID 29803203, 2019). "We investigated the efficacy of insulin suppression on lipolysis and assessed the hypothesis that FFA-stimulated insulin secretion might play a vital role on the progression of insulin resistance." (PMID 31499737, 2019). "Insulin stimulates testosterone production and insulin resistance may impair this process in the Leydig cells." (PMID 31351493, 2019). "Although the pathological mechanism is presently unclear, the insulin resistance has been attributed to changes in insulin signalling that occur downstream from the insulin receptor in the insulin receptor substrate (IRS), phosphatidylinositol-3-kinase (PI3K) and protein kinase B (AKT) pathway." (PMID 31195596, 2019). "In line with the impaired insulin signalling in metabolic tissues and hyperinsulinemic–euglycemic clamp studies, p110αDEL mice displayed systemic insulin resistance at all of the time points tested." (PMID 30948720, 2019). "As both leptin and adiponectin are known to influence insulin sensitivity of metabolic tissues, reduced levels of leptin and adiponectin might play a role in the development of insulin resistance in liver and skeletal muscle, as seen in p110αDEL mice." (PMID 30948720, 2019). "Insulin resistance, the condition in which a cell, tissue, or organism fails to respond appropriately to insulin, is a hallmark for the development of type 2 diabetes and a major contributor to the pathogenesis of NAFLD." (PMID 31024446, 2019). "We hypothesized that individuals with obesity or T2DM would have reduced skeletal muscle Nur77 and NOR1 gene and protein expression in response to insulin stimulation, related to the subject's degree of insulin resistance." (PMID 30912283, 2019). "However, specific role of insulin in safeguarding cognitive function has been more clearly confirmed by studies showing that PD patients with dementia are prone to comorbid insulin resistance, even when they were unaffected by diabetes." (PMID 31474827, 2019). "CKD is associated with insulin resistance and, in advanced CKD, decreased insulin degradation." (PMID 31821152, 2019). "After it was reported that myoinositol improves insulin sensitivity in patients with PCOS, researchers began to analyze whether myoinositol can prevent or reduce insulin resistance in patients at risk for developing or with gestational diabetes." (PMID 31886278, 2019). "The elevation of insulin secretion may be compensatory for the increase of insulin resistance in the KTR group." (PMID 31252561, 2019). "Insulin levels were significantly higher in NGT patients reflecting the compensatory pancreatic response in the face of reduced Si similar to other conditions of insulin resistance like obesity." (PMID 31620090, 2019). "The role oxidative stress plays in type 2 diabetes could be bidirectional, as it is reported that increased ROS level is an important trigger for insulin resistance and there is also evidence indicating the enhancement of insulin sensitivity by ROS." (PMID 31949875, 2019). "To exclude insulin resistance and self-immunity as possible confounders and to investigate the effects of GLP1 on rat pancreatic islets, we constructed severe insulin-deficient diabetic rat models induced by injecting a single dose of intraperitoneal STZ (60 mg/kg)." (PMID 31001561, 2019).
Insulin resistance (continued). "As in peripheral tissues, insulin resistance, the reduced ability of insulin to exert its actions on target tissues, may develop in the brain." (PMID 31849810, 2019). "Other than being obese and having high insulin resistance, impaired insulin secretion in leanness may be involved in the onset of GDM and affected individuals who are lean prior to pregnancy may progress early on to GDM or worsen perinatal prognosis." (PMID 31275653, 2019). "The impact of dyslipidemia on incident DM may be mediated by the inhibition of insulin secretion or the development of insulin resistance." (PMID 31608013, 2019). "This may be explained by insulin resistance, with increased insulin levels, increased cortisol levels resulting from alterations in glucose intake, higher TNFR-2 receptor expression, hypogonadism, and decreased testosterone levels reported in DM1." (PMID 31849810, 2019). "The objectives of this manuscript are to revise the studies on the association between vitamin D status and obesity and obesity-induced insulin resistance, and to explore the pathophysiological mechanism(s) by which vitamin D modulates insulin sensitivity and glycemic control in obese individuals." (PMID 31266190, 2019). "Insulin resistance is likely established in an individual for several years before hyperglycemia develops, hence, indices of glucose tolerance, insulin sensitivity, and β-cell function are valid measurements to assess risk of metabolic diseases, such as type 2 diabetes and MetS." (PMID 31547352, 2019). "In addition, adipokines secreted by visceral adipose tissue, such as leptin, adiponectin, and TNF-α, play a key role in the tissue sensitivity to insulin, favoring the onset of insulin resistance and tissue inflammation." (PMID 30944697, 2019). "An Aloe vera (AG) gel complex (Aloe QDM complex) assessed in a randomized control trial showed borderline significant reductions in body weight, body fat mass, FBG, fasting serum insulin, and Homeostasis Model of Assessment-Insulin Resistance (HOMA-IR) after eight weeks of treatment [1057]." (PMID 31575072, 2019). "Under insulin resistance and compensatory hyperinsulinemia condition, insulin might have a potential to bind to IGF-receptors and stimulate the proliferation of keratinocytes and fibroblasts." (PMID 31824416, 2019). "Body weight, epididymal fat and liver weight, glucose, lipid, insulin, and histologic characteristics were evaluated to determine the effect of PF on insulin resistance by analyzing the proportion of macrophages in epididymal fat and liver and measured inflammatory gene expression." (PMID 31212747, 2019). "However, it is well-recognized that insulin stimulates Hif-1, whereas intermittent hypoxia induces insulin resistance in mice." (PMID 31354511, 2019). "The insulin secretion/insulin resistance (disposition) index increased significantly." (PMID 31470605, 2019). "The imbalance between excessive caloric intake and physical inactivity in obesity is highly correlated with elevated insulin levels, insulin resistance and hyperglycemia which can lead to type II diabetes mellitus (T2DM) in experimental animals as well as in human subjects." (PMID 30759730, 2019). "Insulin secretion in type 2 diabetes is lower in Asians than in Caucasians, and therefore slightly increased insulin resistance may result in glucose intolerance in Asians." (PMID 30677099, 2019). "In order to compensate for insulin resistance to maintain normal glucose concentrations, β-cells produce more insulin but ultimately fail to do so and T2D may be diagnosed." (PMID 30944826, 2019). "Interestingly, IKKβ has been reported to induce insulin resistance (IR) and the diminished insulin-dependent stimulation of glucose uptake, which is known to induce cardiac dysfunction by itself." (PMID 31616027, 2019).